ENG (endoglin)
Diseases named in the same sentence as ENG in open-access papers (continued):
Sharing a sentence is not in itself a finding about the gene and the disease.
hereditary hemorrhagic telangiectasia (continued). "Microparticle-mediated endoglin delivery may also have potential therapeutic implications in angiogenic disorders associated with abnormal endoglin function, such as hereditary hemorrhagic telangiectasia." (PMID 26786759, 2016). "Endoglin (ENG) is a causative gene of type 1 hereditary hemorrhagic telangiectasia (HHT1)." (PMID 24520391, 2014). "Hereditary hemorrhagic telangiectasia (HHT) is an autosomal dominant vascular disorder caused by pathogenic variants in ENG (HHT1) and ACVRL1 (HHT2), with distinct phenotypic expressions." (PMID 40648782, 2025). "Endoglin is implicated in several angiogenesis-related conditions, including the rare vascular disease hereditary hemorrhagic telangiectasia (HHT), a heterogeneous autosomal dominant disorder with prevalence estimated at 1 in 5000." (PMID 41039222, 2025). "The most frequently associated genetic mutations involve the hereditary hemorrhagic telangiectasia (HHT) genes (ENG, ACVRL and SMAD4) and RASA1 -- which are also implicated in brain AVM and VOGM, respectively." (PMID 38506930, 2024). "Loss of function mutations in ALK1 and ENG cause hereditary hemorrhagic telangiectasia (HHT), a genetic bleeding disorder characterized by EC proliferation and migration defects that leads to the development of systemic vascular lesions." (PMID 36631513, 2023). "Hereditary hemorrhagic telangiectasia (HHT) is a rare inherited disease due to heterozygous loss-of-function mutations on the BMP9/10 pathway (ENG, ACVRL1 or MADH4 mainly)." (PMID 38143764, 2023). "Hereditary Hemorrhagic Telangiectasia (HHT) is an autosomal dominant disorder caused, in more than 80% of cases, by mutations of either the endoglin (ENG) or the activin A receptor-like type 1 (ACVRL1) gene." (PMID 35628811, 2022). "ACVRL1 or ENG genetic variants have been found in patients with hereditary hemorrhagic telangiectasia (HHT) combined with PAH." (PMID 35811711, 2022). "The Endoglin (ENG) gene is one of the main disease-causing genes for hereditary hemorrhagic telangiectasia (HHT), also known as Osler–Weber–Rendu syndrome, a rare vascular disorder causing abnormal vessel formation." (PMID 35387445, 2022). "Finally, low expression of Endoglin is associated with improved clinical outcome in several cancers, and cancer patients with concurrent hereditary hemorrhagic telangiectasia (HHT), a hereditary condition caused by deleterious ENG mutations show longer survival." (PMID 33627649, 2021). "It has been shown that in hereditary hemorrhagic telangiectasia (HHT), a disease caused by mutations in the endoglin gene, patients infected with SARS-CoV-2 suffer milder symptoms with lower clinical impact than the general population." (PMID 34073119, 2021). "AVM is also a component of several hereditary disorders, like hereditary hemorrhagic telangiectasia (HHT, also known as Osler–Weber–Rendu disease), Wyburn–Mason syndrome, and Sturge–Weber syndrome characterized by mutations of endoglin (ENG) or Alk1 (ACVRL1)." (PMID 32677965, 2020). "Hereditary hemorrhagic telangiectasia (HHT), also known as Rendu-Osler–Weber syndrome, is a rare genetic disease, which is characterized by mutations in the endoglin (HHT-1) or ALK-1 (HHT-2) genes." (PMID 32059544, 2020). "Hereditary hemorrhagic telangiectasia (HHT), a rare autosomal dominant disease mostly caused by mutations in three known genes (ENG, ACVRL1, and SMAD4), is characterized by the development of vascular malformations (VMs)." (PMID 32842615, 2020). "Thus, mutations in the human ENDOGLIN gene (ENG) cause Hereditary Hemorrhagic Telangiectasia (HHT) type 1, a dominant vascular disease that present with nose and gastrointestinal bleedings, telangiectases on skin and mucosa, and arteriovenous malformations in lung, liver, and brain." (PMID 32316263, 2020). "Endoglin mutations cause hereditary hemorrhagic telangiectasia (HHT), which is an autosomal-dominant disorder." (PMID 30406116, 2018).
hereditary hemorrhagic telangiectasia (continued). "In addition, mutations in the human endoglin gene (ENG) are the underlying cause of hereditary hemorrhagic telangiectasia (HHT) type 1 (HHT1), an autosomal-dominant disorder characterized by the presence of arteriovenous malformations (AVMs) in different organs." (PMID 30108051, 2018). "In human, ENG haploinsufficiency is associated with type 1 hereditary hemorrhagic telangiectasia (HHT), also known as Osler-Rendu-Weber Syndrome, which is an autosomal dominant disease." (PMID 29497632, 2017). "Haploinsufficiency of ENG results in Hereditary Hemorrhagic Telangiectasia (HHT), characterized by a loss of arteriovenous identity and aberrant vSMC incorporation in fragile vessels." (PMID 28859090, 2017). "Hereditary hemorrhagic telangiectasia (HHT) is a genetic disorder inherited in an autosomal dominant manner and caused by mutations in the genes encoding endoglin and activin receptor-like kinase type 1." (PMID 27878613, 2017). "Mutations in Alk1, its co-receptor endoglin or the common effector Smad4 are involved in the pathogenesis of hereditary hemorrhagic telangiectasia (HHT), a vascular condition characterized by arteriovenous malformations (AVM)." (PMID 27517154, 2016). "Genetic mouse models of AVMs include those for hereditary hemorrhagic telangiectasia (HHT; Rendu-Osler-Weber syndrome) with mutations in endoglin or activin receptor-like kinase 1 (Alk1) or proteins regulated by Alk1." (PMID 25993289, 2015). "Hereditary hemorrhagic telangiectasia (HHT) is an autosomal dominant vascular disorder caused by mutations in ENG, ACVRL1 and SMAD4, which function in regulating the transforming growth factor beta and bone morphogenetic protein signaling pathways." (PMID 27081547, 2015). "Hereditary hemorrhagic telangiectasia (HHT) is an autosomal dominant disorder of angiodysplasia, affecting 1 in 5–8,000 people, most commonly caused by mutations in ENG or ALK1/ACVRL1 gene." (PMID 23710379, 2013). "Genetic analysis identified a mutation in the endoglin gene, typical for patients with hereditary hemorrhagic telangiectasia (HHT), also called Osler–Weber–Rendu syndrome." (PMID 23351611, 2013). "Hereditary Hemorrhagic Telangiectasia (HHT) is a rare vascular disease mainly caused by pathogenic mutations in ACVRL1 and ENG genes." (PMID 40681766, 2025). "Hereditary hemorrhagic telangiectasia (HHT), a genetic disorder may be caused by mutations in genes such as ENG (encoding endoglin) or ACVRL1 (ALK1), and less commonly SMAD4, is one condition that predisposes individuals to multiple AVMs." (PMID 41555917, 2025). "Another disease that involves vascular malformations in the lungs (and other organs) is hereditary hemorrhagic telangiectasia (HHT), which is mainly caused by mutations in ALK1 and endoglin." (PMID 41378712, 2025). "Depletion of endothelial endoglin in adult mice as a model of hereditary haemorrhagic telangiectasia, leads to pericyte detachment in the arteriole-capillary transition (ACT) zone." (PMID 40738972, 2025). "Endoglin plays a pivotal role in angiogenesis and in maintaining the structural integrity of the blood vessels; certain mutations of ENG are associated with hereditary hemorrhagic telangiectasia (HHT)." (PMID 38534334, 2024). "In hereditary hemorrhagic telangiectasia (HHT), mutations in ENG or ACVRL1 are frequently observed, while SMAD4 mutations affect a small percentage of patients." (PMID 38673717, 2024). "In hereditary hemorrhagic telangiectasia, regulation is disrupted due to mutations in the BMP-9/10 pathway, namely in the type I receptor ALK1 or the co-receptor endoglin." (PMID 39464140, 2024). "ENG and ALK1 are causative genes of hereditary hemorrhagic telangiectasia (HHT), which is a familial disorder with high prevalence of bAVMs." (PMID 37214790, 2023).
hereditary hemorrhagic telangiectasia (continued). "Hereditary haemorrhagic telangiectasia (HHT) is an autosomal dominant multisystem vascular dysplasia arising from a single heterozygous loss-of-function variant (“mutation”), usually in ENG, ACVRL1, or SMAD4." (PMID 38137783, 2023). "In addition, mutations in the endoglin gene were identified in patients with hereditary hemorrhagic telangiectasia (HHT), an autosomal dominant vascular dysplasia." (PMID 36844233, 2023). "Patients with hereditary hemorrhagic telangiectasia (HHT) have arteriovenous malformations (AVMs) with genetic mutations involving the activin-A receptor like type 1 (ACVRL1 or ALK1) and endoglin (ENG)." (PMID 35380991, 2022). "Mutations in ENG and ACVRL1 lead to similar phenotype and account for 85% of hereditary hemorrhagic telangiectasias." (PMID 35281255, 2022). "Hereditary Hemorrhagic Telangiectasia (HHT) is an autosomal dominant, inherited disease, most commonly caused by mutations in the genes encoding endoglin (ENG) or activin A receptor type II-like 1 (ACVRL1, or ALK1)." (PMID 36142926, 2022). "All publications from the ACVRL1, ENG and SMAD4 Mutation Databases and publications searched for terms “hereditary hemorrhagic telangiectasia” and “founder” in PubMed and Scopus, respectively, were extracted." (PMID 33919892, 2021). "No other variants were observed in the rest of the genes included in the panel, including genes related to Hereditary Hemorrhagic Telangiectasia (ENG, ACVLR1)." (PMID 32348326, 2020). "Hereditary hemorrhagic telangiectasia types 1 and 2 (HHT1, HHT2) and familial pulmonary arterial hypertension (FPAH) have been associated with mutations in ENG, ACVRL and BMPR2, respectively." (PMID 33195419, 2020). "Two other genes, ACVRL1 and ENG, which also encode receptors belonging to the TGF-β superfamily, have been more recently identified in PAH accompanying hereditary hemorrhagic telangiectasias (HHT)." (PMID 29743074, 2018). "In addition, mutations of the genes ACVRL1 and ENG, encoding the co-receptor endoglin, are responsible of the Rendu-Osler syndrome also known as hereditary hemorrhagic telangiectasia (HHT)." (PMID 30165893, 2018). "Hereditary hemorrhagic telangiectasia (HHT) is caused by mutations in TGFβ/BMP9 pathway genes, most commonly ENG (OMIM 131195) or ACVRL1 (ALK1, OMIM 601284)." (PMID 29932521, 2018). "Most notably, mutations in the endoglin (ENG) gene lead to the autosomal dominant vascular disorder, hereditary hemorrhagic telangiectasia type 1 (HHT1)." (PMID 25114380, 2014). "Endoglin and ALK1, a TGFβ family type I receptor, show high affinity for BMP9 and BMP10, and are both associated with the inherited vascular disorder Hereditary Haemorrhagic telangiectasia (HHT)." (PMID 22745736, 2012). "Hereditary Hemorrhagic Telangiectasia (HHT) is an autosomal dominant and age-dependent vascular disorder characterised mainly by mutations in the Endoglin (ENG) or activin receptor-like kinase-1 (ALK1, ACVRL1) genes." (PMID 18673552, 2008). "Additionally, mutations in BMP9 or the genes encoding BMP‐9/‐10 receptors, ACVRL1 (encoding ALK1) and ENG (encoding endoglin), lead to hereditary hemorrhagic telangiectasia (HHT), a rare genetic disease that is characterized by arteriovenous malformations (AVMs) and internal bleeding." (PMID 39921464, 2025). "Interestingly, mutations in GDF2, as well as in ACVRL1, ENG and SMAD4 are also known to be causal of hereditary haemorrhagic telangiectasia (HHT)." (PMID 41222740, 2025). "Notably, it enabled the identification of a single-exon deletion in the ENG gene in a family with Rendu-Osler-Weber disease, which had been missed by SRS due to partial enrichment of the deleted exon, thus masking the CNV during variant calling." (PMID 41300778, 2025). "Notably, endoglin is involved in hemostasia regulation via platelet adhesion to ECs and in vascular pathologies, such as the hereditary hemorrhagic telangiectasia." (PMID 36869357, 2023).
hereditary hemorrhagic telangiectasia (continued). "Conversely, mutation of the BMP receptors activin-like kinase 1 (ALK1), endoglin (ENG), or the downstream effector, SMAD family member 4 (SMAD4) leads to hereditary hemorrhagic telangiectasia (HHT), characterized by fragile and leaky arterial-venous malformations (AVMs)." (PMID 37490341, 2023). "Following the identification of BMPR2 haploinsufficiency as a molecular mechanism of disease, additional causal variants were described in genes encoding the ALK1 (ACVRL1) and Endoglin (ENG) receptors, which have been observed in association with hereditary haemorrhagic telangiectasia (HHT)." (PMID 35772304, 2022). "Mutations in ENG lead to the inherited vascular disorder hereditary hemorrhagic telangiectasia characterized by local telangiectases and larger arteriovenous malformations (AVMs); but how ENG functions to regulate the adult vasculature is not understood." (PMID 31805812, 2020). "PAH can co-occur with hereditary hemorrhagic telangiectasia (HHT), a disease characterized by arteriovenous malformations in the lung, brain, liver, skin, and mucus membranes which implicates ACVRL1 (ALK1) and ENG mutations in the pathogenesis of PAH24–26." (PMID 33150157, 2020). "The pathophysiological importance of endoglin in vascular biology is clearly established in humans by the linkage between heterozygous mutations in the endoglin gene and the occurrence of the hereditary hemorrhagic telangiectasia (HHT) or Rendu–Osler–Weber syndrome." (PMID 29080903, 2018). "Hereditary hemorrhagic telangiectasia (HHT) is a potentially life-threatening genetic vascular disorder caused by loss-of-function mutations in the genes encoding activin receptor-like kinase 1 (ALK1), endoglin, Smad4, and bone morphogenetic protein 9 (BMP9)." (PMID 27874028, 2016). "Endoglin is a type III TGFβ auxiliary receptor that is upregulated in endothelial cells during angiogenesis and, when mutated in humans, results in the vascular disease hereditary hemorrhagic telangiectasia (HHT)." (PMID 25909848, 2015). "Hereditary hemorrhagic telangiectasia (HHT), which is caused by pathogenic variants in genes such as ENG (endoglin), ACVRL1 (ALK1), and less commonly SMAD4, is one such condition that predisposes individuals to multiple AVMs." (PMID 41555917, 2025). "Hereditary hemorrhagic telangiectasia (HHT) is an autosomal dominant disorder which is associated with severe abnormalities in the microvascular network and linked to mutations in ACVRL1 and ENG genes." (PMID 35440116, 2022). "That is, hereditary hemorrhagic telangiectasia (or HHT) caused by mutations in ACVRL1 and ENG, involves arteriovenous malformations mainly affecting the lungs and liver; or, mutations in BMPR2 may lead to pulmonary hypertension with no impairment of the endothelium in other organs." (PMID 35163400, 2022). "These include hereditary hemorrhagic telangiectasia (HHT) and capillary malformation-arteriovenous malformation (CM-AVM) which have been attributed to inherited mutations in RASA1, endoglin, and activin receptor-like kinase 1 (ALK1)." (PMID 36198763, 2022). "In humans, haploinsufficiency of endoglin is responsible for one of the most common types of hereditary hemorrhagic telangiectasia (HHT)." (PMID 33800564, 2021). "Mutations in the ENG and ACVRL1 genes (encoding for ENG and ALK1) cause Hereditary Hemorrhagic Telangiectasia (HHT), which is a genetic form of AVM development." (PMID 33716786, 2021). "Pathogenic mutations in TGF-β signaling, such as ENG, ALK1 gene mutations, are associated with type 1 and type 2 hereditary hemorrhagic telangiectasia (HHT), as well as Loeys-dietz syndrome with cerebrovascular events." (PMID 33072751, 2020). "Mutations in ACVRL1 and ENG have been reported in PAH patients and in patients with PH in association with hereditary hemorrhagic telangiectasia (HHT)." (PMID 33256119, 2020).
hereditary hemorrhagic telangiectasia (continued). "Hereditary hemorrhagic telangiectasia (HHT) gene variants in the activin receptor-like kinase 1 (ACVRL1) and endoglin (ENG) have been identified in PAH patients." (PMID 31382961, 2019). "The endogolin (ENG)g (*131195), activin A receptor type 1 (AVCRL1) (*601284), SMAD4 (SMAD family member 4) (*600993), and growth differentiation factor 2 (GDF2) (*605120) genes have been identified as the underlying cause of hereditary hemorrhagic telangiectasia." (PMID 31594285, 2019). "Arteriovenous malformations are very frequent in patients who suffer from Hereditary Hemorrhagic Telangiectasia (HHT), a disease associated with reduced ALK1, ENG, or SMAD4 function." (PMID 29230182, 2017). "Moreover, other regionalized vascular disorders such as hereditary hemorrhagic telangiectasia (HHT) and pulmonary arterial hypertension (PAH) are mainly caused by mutations in the BMP receptors ACVRL1 (encoding ALK1) or ENG (encoding Endoglin) and BMPR2 respectively." (PMID 27724845, 2016). "The 24 patients receiving elective surgery were aged 17–80 years (mean 39 years), 11 (46%) were male, and 17 had confirmed hereditary hemorrhagic telangiectasia (HHT) spanning ACVRL1, ENG and SMAD4 genotypes." (PMID 39777301, 2025). "Hereditary hemorrhagic telangiectasia (HHT, Osler–Weber–Rendu syndrome) is an autosomal-dominant vascular disorder caused by heterozygous loss-of-function mutations in activin receptor-like kinase 1 (ALK1), endoglin (ENG), or SMAD4." (PMID 37219736, 2023). "ALK1 and ENG also have significant levels of expression within the pulmonary endothelium and mutations in each of these proteins have been linked to the development of PAH as well as hereditary hemorrhagic telangiectasia (HHT)." (PMID 38126077, 2023). "Increased level of endoglin and the occurrence of PAH were due to highly oxidative stress in hereditary hemorrhagic telangiectasia." (PMID 37646902, 2023). "Haploinsufficiency for Endoglin (ENG) and activin A receptor type II-like I (ACVRL1/ALK1) lead to the formation of weak and abnormal vessels in hereditary hemorrhagic telangiectasia (HHT)." (PMID 36142926, 2022). "Hereditary Hemorrhagic Telangiectasia (HHT) is an autosomal-dominant genetic disorder involving defects in two predominant genes known as endoglin (ENG; HHT-1) and activin receptor-like kinase 1 (ACVRL1/ALK1; HHT-2)." (PMID 35665360, 2022). "Variants in two other genes in the transforming growth factor-beta (TGF-β) superfamily, activin A receptor type II-like 1 (ACVRL1), and endoglin (ENG) contribute to ~ 0.8% of PAH cases, especially PAH associated with hereditary hemorrhagic telangiectasia (APAH-HHT)." (PMID 33971972, 2021). "Mutations in endoglin gene (ENG) or in the closely related TGF-β receptor type I ACVRL1/ALK1 are responsible for a rare dominant vascular dysplasia, the Hereditary Hemorrhagic Telangiectasia (HHT), or Rendu-Osler-Weber syndrome." (PMID 27010826, 2016). "Although the majority of BAVMs arise sporadically, they also occur in patients with Hereditary Hemorrhagic Telangiectasia (HHT), a Mendelian disorder inherited in an autosomal dominant fashion and caused by mutations in one of three genes (ACVRL1, ENG and SMAD4) in the TGFβ signaling pathway." (PMID 24098321, 2013). "Moreover, mice carrying a single copy of the endoglin gene show a tendency to develop hereditary hemorrhagic telangiectasia (HHT) phenotype as they age, with extensive dilated and weak-walled vessels." (PMID 23894375, 2013). "OECs from patients with hereditary haemorrhagic telangiectasia (HHT) revealed abnormalities compatible with vascular lesions, such as decreased endoglin expression, impaired TGF-β signalling, disorganised cytoskeleton, and failure to form cord-like structures." (PMID 22550504, 2012).